Y_RNA (Y RNA )
Gene: Miscellaneous RNA gene on chromosome 3 (193,624,189 to 193,624,301, forward strand). Ensembl gene ENSG00000207370.
Homologues: Orthologues: chimpanzee Y_RNA (99% identical), macaque Y_RNA (91% identical), guinea pig Y_RNA (89% identical), guinea pig Y_RNA (87% identical). Paralogues in human: RNY1 (88% identical), Y_RNA (88% identical), RNY1P11 (87% identical), Y_RNA (87% identical), Y_RNA (86% identical), Y_RNA (85% identical), Y_RNA (84% identical), RNY1P8 (83% identical), Y_RNA (83% identical), Y_RNA (82% identical), RNY1P5 (81% identical), Y_RNA (81% identical), and 95 more.